PTCH1 (patched 1)
Diseases named in the same sentence as PTCH1 in open-access papers (continued):
Sharing a sentence is not in itself a finding about the gene and the disease.
breast carcinoma (continued). "Our Cox Proportional Hazards analysis revealed that PTCH1 and CTNBB1 pose the highest risk for resistance, with hazard ratios over 1.5 in ER+/HER2- breast cancer patients." (PMID 37700842, 2023). "Im and colleagues showed that in 190 over 334 tissue microarrays from breast cancer patient samples the overexpression of Ptch1 was significantly correlated with a more aggressive tumor growth, advanced cancer stages and lymph node metastasis." (PMID 35631574, 2022). "In conclusion, SETDB2 interacts with ΔNp63α, methylates and stabilizes ΔNp63α to upregulate the transcription of the Hedgehog signaling pathway-associated genes CXCR4, PTCH1 and GLI2, which promote breast cancer stem cell maintenance and tumor initiation." (PMID 32549764, 2020). "These experiments strongly suggest that TSPAN8 together with ATXN3 promote the Hedgehog signaling and breast cancer progression by enhancing PTCH1 and SHH expression." (PMID 31253779, 2019). "Although further efforts should be applied to understand the role of PTCH1 in breast cancer, we believe that the present study suggests unprecedented value in assessing PTCH1 in breast cancer patients." (PMID 31704974, 2019). "Since only a few studies have focused on this gene in breast cancer, we selected PTCH1 for further analyses." (PMID 31704974, 2019). "Elevated expression of PTCH1, which suggests activation of the canonical Hh pathway, was correlated with the Ki-67 index, and with shorter metastasis-free survival in luminal-B breast cancer patients." (PMID 31027259, 2019). "This was confirmed in a recent study that was performed on 150 fresh tumors from breast cancer patients, which reported that Ptch1 was significantly overexpressed in tumors, as compared to in corresponding normal mammary tissues." (PMID 30110910, 2018). "Disruption of either Ptch1 or Gli-2 leads to defects in ductal morphogenesis, which suggests a role for abnormal Hh signaling in breast cancer formation." (PMID 29069872, 2017). "Mukherjee reported that Ptch1 and Smo are expressed at low level in the normal tissue, and Smo is over-expressed in nearly 70% of ductal carcinomas and in about 30% of metastasis breast cancer tissues." (PMID 29069872, 2017). "Genetic alternations in components of the HH pathway, including loss of PTCH1 or GLI1 amplification, were suggested to result in breast cancer." (PMID 27689403, 2016). "Conversely, several studies reported the overexpression of an Hh ligand, often Shh, and the Hh transcriptional targets GLI1 and Ptch1, thus activating the Hh pathway, in breast cancer." (PMID 26843616, 2016). "Alternatively, several studies reported overexpression of Hh ligands, often Shh, and of the Hh transcriptional targets GLI1 and Ptch1 and, thus, the activation of the Hh pathway in breast cancer." (PMID 26843616, 2016). "Expression of Shh, Ptch-1, Gli-1, and Smo mRNA in breast cancer tissue was also shown to correlate with disease recurrence." (PMID 26389956, 2015). "A role for abnormal Shh signaling activity in breast cancer development was first reported using transgenic mouse models, where Ptch-1 haploinsufficiency or ectopic expression of Smo lead to distinct forms of mammary ductal dysplasia." (PMID 25889650, 2015). "It was observed that expression of Ptch-1 was significantly decreased in breast cancer compared to mammary hyperplasia." (PMID 26389956, 2015). "Ptch-1 was shown to be increased significantly in luminal breast cancer cell lines MCF7, T47D, 13762 and HER2+ cell line SKBR3." (PMID 26389956, 2015). "We also treated breast cancer cells with the Shh ligand to examine the effect of Shh on Gli1 and Ptch1 mRNA expression." (PMID 24889938, 2014). "Mutations in PTCH1, SMO and SHH genes have been examined in breast cancer: some studies found mutations, while others did not." (PMID 25503972, 2014).
breast carcinoma (continued). "The dual function of PTCH1 as a multidrug efflux pump and a hedgehog receptor, and the active involvement of CTNNB1 in breast cancer strongly indicate that PTCH1 and CTNNB1 can be potential drug targets to overcome chemoresistance in ER +/HER2- breast cancer patients." (PMID 37700842, 2023). "In addition to PTCH1, high SHH, SMO, GLI1, and GLI2 expression levels were all associated with a poor prognosis in breast cancer patients." (PMID 36142286, 2022). "This is supported by findings that SHH, PTCH1, and GLI1 mutations are exceedingly rare in breast cancer which argues against the potential involvement of mutational activation of the SHH pathway in breast cancer." (PMID 32957513, 2020). "Interestingly, we found that Gli1 was significantly up‐regulated in breast cancer tissues, whereas PTCH1, SMO, Gli1 and HHIP at mRNA and protein levels were all down‐regulated after controlling for EGOT overexpression." (PMID 32150666, 2020). "A higher ratio of PTCH1 mutations was found in luminal B breast cancer without Her-2/neu overexpression (67%) and triple-negative breast cancer (TNBC, 62%) compared with other subtypes." (PMID 31704974, 2019). "According to our data, the function of PTCH1 in breast cancer was presumed to depend on mutation frequency, not the expression level." (PMID 31704974, 2019). "We conducted deep targeted sequencing of the PTCH1 gene from 44 breast cancer patient samples." (PMID 31704974, 2019). "Indeed, in 2013, a study from Korea examined 334 cases of breast cancer and found that Ptch1 was overexpressed in 190 of them, and was significantly correlated with lymph node metastasis, advanced cancer stages, and more aggressive tumor behavior." (PMID 30110910, 2018). "The Ptch1 locus is one of the most commonly detected changes among the tumor suppressor genes, which occur in about 19% of human breast cancers and in up to 33% of breast cancer cell lines." (PMID 29069872, 2017). "A study suggested that the mRNA of Ptch-1 and Gli-1 in core needle biopsy would provide a useful tool for surgeons and patients for the selection of treatment options in the clinical management of breast cancer." (PMID 26389956, 2015). "Methylation of the PTCH1 promoter inhibits PTCH1 expression in breast cancers." (PMID 24963031, 2014). "The two proteins, ZP4 and PTCH1, could therefore potentially represent an unknown link between MHT usage, female tissues, and mammographic breast density all leading to increased risk of breast cancer." (PMID 35033985, 2022). "We observed that several genes including PTCH1, ATXN1, DLL4, SOX2 and DACH1 were differentially regulated in tbLCM-treated breast cancer cells as compared to those treated with tnLCM or BM control." (PMID 38581619, 2024). "The hazard ratios for PTCH1, and CTNNB1 in three different arms of treatment in ER+/HER2- breast cancer patients." (PMID 37700842, 2023). "Lastly, Cox Proportional Hazards Regression put forward PTCH1 and CTNNB1 as key markers of resistance to neoadjuvant therapy in ER+/HER2- breast cancer." (PMID 37700842, 2023). "The key finding of this study is the emergence of PTCH1 and CTNBB1 as key predictors for resistance to taxane-based neoadjuvant therapy in ER+/HER2- breast cancer." (PMID 37700842, 2023). "In conclusion, PTCH1 and CTNBB1 emerge as key markers of resistance to taxane-based neoadjuvant chemotherapy in ER+/HER2- breast cancer patients." (PMID 37700842, 2023). "PTCH1 and CTNNB1 did not exhibit an increased risk in the control group and endocrine therapy group, further strengthening the predictive potential of PTCH1 and CTNNB1 in ER+/HER2- breast cancer." (PMID 37700842, 2023). "We found that normal breast tissue and breast cancer tissue expressed significantly different levels of SHH, PTCH1, SMO, GLI1, and GLI2 (p < 0.05)." (PMID 36142286, 2022). "First, we analyzed the expression of SHH, PTCH1, SMO, GLI1, and GLI2 in normal breast and breast cancer tissues through the Oncomine database." (PMID 36142286, 2022).
breast carcinoma (continued). "In breast cancer, Gant61 treatment decreased cell proliferation by reducing GLI1 and PTCH1 gene expression and inhibited GLI1 nuclear translocation." (PMID 33396427, 2020). "Our analyses of human breast cancer specimens revealed positive correlation among the expression levels of TSPAN8, PTCH1, SHH, and ATXN3." (PMID 31253779, 2019). "To determine the clinical relevance of TSPAN8- and ATXN3-regulated PTCH1/SHH stability, we performed IHC staining of 90 breast cancer specimens and found that the expression of TSPAN8 in the tumor tissue was higher than that in the adjacent non-tumor tissue." (PMID 31253779, 2019). "However, the possibility of artifacts could not be completely excluded, and further study of PTCH1 mutations in breast cancer patients is necessary." (PMID 31704974, 2019). "However, there is a lack of research on PTCH1 mutations in breast cancer." (PMID 31704974, 2019). "Accordingly, expression levels of TSPAN8, PTCH1, SHH, and ATXN3 are positively correlated in human breast cancer specimens, and high TSPAN8 and ATXN3 expression levels correlate with poor prognosis." (PMID 31253779, 2019). "Expression analysis of key markers of the activity of the HH signaling pathway i.e. GLI1 and PTCH1, revealed higher expression in the tamoxifen resistant LCC2 breast cancer cells compared to the parental, tamoxifen sensitive MCF7 cells." (PMID 27689403, 2016). "Deletion analysis of PHF2, FANCC, PTCH1 and XPA were examined in a subset of 47 early-onset (group-A: ≤ 40 years) and 59 late-onset (group-B: > 40 years) breast carcinomas using both microsatellite and exonic markers." (PMID 18990233, 2008). "Despite the p-values for AUCs of some genes such as AP3B2, BLOC1S1, NUDT13, PTCH1, and ZNF609 being statistically significant in all three breast cancer subtypes, their significance in HER2+ cancers and TNBC were much lower compared to that in ER+/HER2- breast cancer patients." (PMID 37700842, 2023). "Therefore, we used the Kaplan–Meier plotter website to analyze the effects of SHH, PTCH1, SMO, GLI1, and GLI2 on the prognosis of breast cancer patients." (PMID 36142286, 2022). "mRNAs of SHH, PTCH1, and GLI1 are highly expressed in breast tumors, inspiring the hypothesis that the SHH pathway may help predict postoperative relapse in breast cancer patients." (PMID 36017236, 2022). "Disorder of the PTCH1 or GLI results in serious defects in ductal morphogenesis and may lead to human breast cancer." (PMID 36017236, 2022). "In the transgenic MMTV-ErbB2 (HER2-positive) mouse model, ΔNp63 supports breast cancer stemness by inducing the elevation of the SHH signaling cascade, inducing the expression of Smoothened (SMO), Protein Patched Homolog 1 (PTCH1), and GLI Family Zinc Finger 2(GLI2)." (PMID 35805056, 2022). "In addition, a positive association between the expression levels of TSPAN8 and SHH, as well as between PTCH1 and ATXN3, in breast cancer specimens was observed." (PMID 31253779, 2019). "PTCH1 protein levels are reduced in 50% of DCIS and invasive breast cancer (IBC), whereas 70% of DCIS and 30% of IBC display aberrant SMO, suggesting that hedgehog activation occurs frequently and early in human breast cancer." (PMID 28275010, 2017). "The database analysis of the Hedgehog pathway markers (SHH, PTCH1, SMO, GLI1, and GLI2) revealed that the Hedgehog pathway is activated in breast cancer tissues, and its high expression is not conducive to a patient’s survival." (PMID 36142286, 2022). "Other Hedgehog signaling factors like SHH, PTCH1, and GLI2 are overexpressed in breast cancer, but their connection to EMT is not well established in breast cancer." (PMID 31075939, 2019).
rhabdomyosarcoma (28 papers, 2010 to 2025). A rare aggressive malignant mesenchymal neoplasm arising from skeletal muscle. "Variants in PTCH1 are associated with rhabdomyosarcoma, other studies report increased expression of PTCH1 in pediatric solid tumors including Wilms tumor." (PMID 33488951, 2020). "Previous studies on rhabdomyosarcoma using PTCH1+/− mice reported the overexpression of mutated PTCH1 transcripts; however, transcripts from the WT allele appeared to be downregulated, resulting in a reduction in functional PTCH1 protein expression." (PMID 30610186, 2019). "The co-presence of Ptch1 and SuFu mutations or Gli1 amplifications is also identified in rhabdomyosarcoma patients." (PMID 31552081, 2019). "Retrospective and human cell line studies of rhabdomyomas and rhabdomyosarcomas noted increased expression of PTCH1 and GLI1, suggesting activation of the Hh pathway." (PMID 36010600, 2022). "In this regard, a recent study has demonstrated the inhibition of human rhabdomyosarcoma xenografts by rapamycin through its effect on HH effector genes such as Gli1 and Gli 2 as well as PTCH1 and PATCH2." (PMID 30858923, 2019). "Significantly, Ptch1+/−/SKH-1 hairless mice also manifest rhabdomyomas/rhabdomyosarcomas that generally appeared subcutaneously, predominantly over the hind limbs." (PMID 26413810, 2015). "In line with our observation, C57BL/6 is known for its resistance to Ptch1+/−-induced rhabdomyosarcomas." (PMID 21533183, 2011). "A role for aberrant Hh signalling in sarcomagenesis was first realised in patients with Gorlin’s syndrome, caused by inactivation of the PTCH1 or SUFU genes, who are predisposed to the development of basal cell carcinomas, medulloblastoma, fibrosarcoma and rhabdomyosarcoma." (PMID 40983796, 2025). "Furthermore, embryonal and alveolar rhabdomyosarcoma frequently have increased expression of PTCH1 and GLI1, transcriptional targets of the Hh signalling pathway, and increased Hh pathway activation is associated with rapid progression and poor outcomes." (PMID 40983796, 2025). "A closer examination of the murine rhabdomyosarcomas from the CAGGS-CreER; R26-SmoM2 mice suggested that they more closely resembled fetal rhabdomyoma histologically than aggressive rhabdomyosarcomas with upregulation of Gli1 and Ptch1 mRNA transcription, indicative of Hh pathway activation." (PMID 36010600, 2022). "Overexpression of GPC5 may accelerate the tumor progression of lymphoma and may enhance the interaction between Patched 1 and Hedgehog signaling in rhabdomyosarcoma." (PMID 35233466, 2022). "Recent work demonstrating the spontaneous development of rhabdomyosarcoma tumors in mice with somatic PTCH1 haploinsufficiency suggests which may provide an ideal model to study rhabdomyosarcoma biology." (PMID 21559211, 2011). "Just as in patients with NBCCS, Ptch1+/−/SKH-1 also spontaneously develops BCCs and other neoplasms such as rhabdomyomas/rhabdomyosarcomas." (PMID 26413810, 2015).
glioma (25 papers, 2010 to 2026). A benign or malignant brain and spinal cord tumor that arises from glial cells (astrocytes, oligodendrocytes, ependymal cells). "Canonical Hh /Gli (glioma-associated) signaling is triggered by the binding of Hh ligands to the twelve-pass transmembrane receptor Patched 1 (PTCH1)." (PMID 37240209, 2023). "PTCH1 knockdown reversed the inhibitory effects of NCOA4 on the malignant behaviours of glioma cells." (PMID 40794264, 2025). "The Hh pathway is a highly conserved signaling pathway, including cell surface receptor Patched-1 (PTCH1), transmembrane receptor Smoothened (SMO), and three glioma associated family transcription factors (GLI1, GLI2, and GLI3)." (PMID 40386398, 2025). "The oncogene smoothened (SMO) specific to C2 has been proposed to transduce Hedgehog signaling (SSH) from tumor suppressor patched 1 (PTCH1) to glioma-associated oncogene GLI family zinc finger (GLI) transcription factors and promote glioma tumorigenesis." (PMID 34540693, 2021). "As a vital negative component of the Sonic Hedgehog (SHH) signaling pathway, PTCH1 participates in the suppression of glioma growth and its inhibition by miR-9 can induce tumor growth both in our study and in a previous report." (PMID 30795814, 2019). "In the presence of Hh, the repressive action of PTCH1 on SMO is removed and the downstream pathway is mediated via the glioma-associated zinc transcription factors, Gli1 and Gli2, which translocate to the nucleus and activate Hh-target genes." (PMID 29423837, 2018). "Expression of Patched 1 (PTCH1), Smoothened (SMO), and glioma-associated zinc transcription factors (Gli1 and Gli2) were assessed in histological sections using immunohistochemistry and immunofluorescence (IF) techniques." (PMID 29423837, 2018). "To investigate whether NCOA4 exerts its inhibitory effect on glioma cell growth via the SHH pathway through the regulation of PTCH1, we knocked down PTCH1 in NCOA4-overexpressing GBM cells by transfecting them with siRNA-PTCH1." (PMID 40794264, 2025). "Moreover, reactive astrocytes produce sonic hedgehog (SHH), which binds smoothened (Smo) and patched-1 (PTCH1) membrane protein on the glioma cell surface, promoting tumor growth, stemness and self-renewal." (PMID 38473812, 2024). "IDHwt GBM PDOXs retained common glioma mutations, including EGFR, MDM4, PTEN, PIK3CA, and PTCH1." (PMID 33009951, 2020). "Knockdown of PTCH1 partially reversed the inhibitory effects of NCOA4 on GBM cell growth and invasion, suggesting that PTCH1, a potential downstream gene of NCOA4, is involved in the suppressive effect of NCOA4 on glioma development." (PMID 40794264, 2025). "In glioma, upregulated miR‐9 inhibits the expression of COL18A1, THBS2, PTCH1 and PHD3, promoting tumorigenesis and angiogenesis." (PMID 39648148, 2024). "miR-9 promotes the angiogenesis and tumorigenesis of glioma by targeting COL18A1, THBS2, PTCH1 and PHD3 directly." (PMID 32958011, 2020). "The role of few important proteins such as PTCH1, SMO, GLI etc., in this pathway has already been identified to be responsible for various types of cancers, such as Glioma, Colon and Pancreatic." (PMID 23935937, 2013). "This differential expression suggests that enhanced PTCH1 expression and SHH pathway activation are involved in brainstem gliomas, potentially explaining the differences in malignant behaviour between brainstem and hemispheric gliomas." (PMID 39568072, 2024). "COL18A1, THBS2, PTCH1 and PHD3 were verified as the direct targets of miR-9, which could elucidate the miR-9-induced malignant phenotypes in glioma cells." (PMID 30795814, 2019).
glioma (continued). "In our study, we confirm that miR-9 can directly bind to the 3’-UTR of COL18A1, THBS2, PTCH1 and PHD3, promote the degradation of these mRNAs and initiate HIF-1α/VEGF signal transduction, thus markedly enhancing tumorigenesis and angiogenesis during the glioma progression." (PMID 30795814, 2019). "Endogenous levels of these targets displayed a significantly negative correlation with miR-9 expression in glioma cells, strongly indicating an inverse relationship between miR-9 and COL18A1, THBS2, PTCH1 and PHD3." (PMID 30795814, 2019).